INS (insulin)
Diseases named in the same sentence as INS in open-access papers (continued):
Sharing a sentence is not in itself a finding about the gene and the disease.
Hyperinsulinemia (continued). "A plausible explanation for the glucose intolerance observed at week 4 despite of hyperinsulinemia and relatively intact insulin sensitivity is probably due to disturbed pulsatile pattern of insulin secretion in HFD mice." (PMID 33817571, 2021). "Hyperinsulinism was diagnosed based on the elevated serum insulin (30.6 pmol/L or 4.4uU/ml) and C-peptide level (0.004 nmol/L or 1.1 ng/mL) with undetectable serum ketone levels." (PMID 33910593, 2021). "Genetic defects in K+ATP channel genes, the insulin gene, or the ER-stress related genes WFS1, YIPF5 and MANF that cause neonatal diabetes and congenital hyperinsulinism have been modeled with hPSCs using diverse strategies." (PMID 33828531, 2021). "This small but significant increase in serum iFGF23 induction by hyperinsulinism in patients with T2DM under euglycemic conditions points to the contribution of insulin to FGF23 production." (PMID 34208131, 2021). "Undetectable β-OH butyrate (< 0.2 mmol/L) with elevated C-peptide (0.007 nmol/L or 2.1 ng/mL) and insulin levels (20.8 pmol/L or 3 uU/mL) in this sample (Table I1 led to the diagnosis of hyperinsulinism." (PMID 33910593, 2021). "This hemodynamic effect is attenuated in conditions of insulin resistance or chronic hyperinsulinemia." (PMID 32664350, 2020). "Insulin signaling, hyperinsulinemia and androgen synthesis are influenced by molecular pathways such as PI3K, MAPK and lipid metabolism." (PMID 32695266, 2020). "In pathological conditions of hyperinsulinemia, insulin can trigger the proliferation pathway activated by IGF-1 in kidney cancer cells lines." (PMID 33008076, 2020). "The actions of insulin on renal sodium handling are preserved during hyperinsulinemia and contribute to increasing sodium reabsorption and increasing glomerular filtration rate, eventually leading to kidney damage." (PMID 33551987, 2020). "When target cells fail to respond effectively to normal insulin concentrations, pancreatic insulin secretion increases in compensation, leading to hyperinsulinemia, which can affect cell proliferation and metabolism, and promote tumor formation." (PMID 31942181, 2020). "Hyperinsulinemia is a condition when the amount of insulin circulating in the blood is higher than expected." (PMID 32993798, 2020). "Fetal hyperinsulinemia has been shown to alter hippocampal development via impaired insulin signaling and reduced neurogenesis in the hippocampus." (PMID 31903710, 2020). "The concern, that hyperinsulinemia might promote arterial disease in diabetic persons, developed in the late 1960s, due to the steady increase of incidences of atherosclerosis in diabetic persons, despite improved glycemia and decreased risk of ketosis due to insulin therapy." (PMID 32819363, 2020). "The phenomenon of IR is accompanied by a pathological insulin secretion after a meal, which is called hyperinsulinemia." (PMID 33233346, 2020). "Naringenin, Ginsenoside Rb1 and Leonurus japonicus Houtt extract prevented hyperinsulinemia, leading to the correction of NAFLD associated metabolic disturbance that was linked to glucose utilization and insulin sensitivity." (PMID 32477116, 2020). "Hyperinsulinemia stimulates the release of intracellular amyloid-β and inhibits its degradation by insulin-degrading enzyme." (PMID 32872655, 2020). "Despite the insulin resistance in metabolic tissues, ovarian cells remain insulin sensitive, which leads to hyperinsulinemia-induced hyperandrogenemia in PCOS." (PMID 33260918, 2020). "Hyperinsulinemia contributes to impaired insulin signaling and metabolism in insulin target tissues." (PMID 32230718, 2020). "Overall, this quantitative microvascular data provide evidence that the flow response to hyperinsulinemia measured in the rat EDL muscle reflects a normal physiological response to insulin." (PMID 31605649, 2020).
Hyperinsulinemia (continued). "Hyperinsulinemia can trigger many physiological effects that drive carcinogenesis, as insulin is a major anabolic hormone that can stimulate cell proliferation." (PMID 32911852, 2020). "Glucose tolerance tests conducted in the HFD-fed obese diabetic mice revealed that nobiletin normalized the impaired high-fat-diet-induced glucose tolerance, while significantly diminishing hyperinsulinemia and improving insulin sensitivity." (PMID 32977511, 2020). "Studies on an enzyme called insulin-degrading enzyme (IDE), which breaks down both insulin and Aβ peptide, showed that in hyperinsulinemia, IDE shifts towards degrading insulin more than Aβ peptide which leads to Aβ peptide accumulation." (PMID 32190448, 2020). "It is now well accepted that fetuses in response to a mild hyperglycemic intrauterine environment exhibit compensatory increases in β-cell mass, pancreatic insulin content and hyperinsulinemia." (PMID 32708537, 2020). "The positive correlations between hyperinsulinemia and androgen levels suggested that insulin contributes to hyperandrogenism in women with PCOS." (PMID 32103756, 2020). "Long-term exposure of hyperinsulinemia is reported to compromise whole-body insulin sensitivity and increase the atherosclerotic milieu." (PMID 33195375, 2020). "Baseline CRP levels were positively correlated (r = 0.3513, p < 0.05) with baseline fasting insulin levels, indicating a close relationship between systemic inflammation and hyperinsulinemia." (PMID 32486256, 2020). "Hyperinsulinemia, an excess of blood insulin levels in relation to circulating glucose levels, is traditionally viewed as compensation for systemic insulin resistance." (PMID 32092075, 2020). "Effective management of NAFLD would require improved glycemic control as well as increased insulin sensitivity, which will reduce hyperinsulinemia." (PMID 32286259, 2020). "Hyperinsulinemia was induced using a gradually increasing dose of insulin, which led to a significant reduction in insulin receptors and a rightward shift in the insulin-glucose transport dose–response curve." (PMID 32326226, 2020). "(The authors have tried to prove hyperinsulinemia in the Indian babies by adjusting insulin levels to the birth weight, but the serum values (which are more relevant) are not statistically different." (PMID 32582754, 2020). "On one hand, it inhibits hyperinsulinemia endogenously by decreasing β cell hyperplasia and insulin secretion." (PMID 32092075, 2020). "Both disease progression with further hepatocellular dysfunction and portal hypertension-related portosystemic shunting of insulin aggravate hyperinsulinemia." (PMID 32092909, 2020). "Metformin, an insulin sensitizer, can reduce hyperinsulinemia to normal levels, but it also reduces hyperandrogenemia." (PMID 31941959, 2020). "Rather, they showed compensatory hyperinsulinemia indicating that higher insulin secretion was able to maintain glucose homeostasis." (PMID 32101528, 2020). "The decrease in skeletal muscle acylcarnitine species upon insulin therefore probably reflects this decreased FFA availability resulting in a transition of lipid towards glucose oxidation induced by hyperinsulinemia." (PMID 32976523, 2020). "Metabolic diseases are characterized by a chronic insulin-resistant state, leading to hyperinsulinemia and potentially to dysglycemia." (PMID 32198362, 2020). "Accumulating epidemiological studies have clearly revealed that hyperinsulinemia, which accompanies these disorders, plays central roles in the development of EC via the insulin-phosphoinositide 3 kinase (PI3K) signaling pathway as a metabolic driver." (PMID 32842547, 2020). "In the human body, when the blood glucose level increases after a meal, the pancreas secrets insulin to lower the glucose level; however, in the case of excessive accumulation of body fat, hyperinsulinemia due to insulin resistance persists for a long time." (PMID 32325640, 2020).
Hyperinsulinemia (continued). "For insulin, we argue here that not only hypoinsulinemia but also hyperinsulinemia is detrimental to body functions." (PMID 32819363, 2020). "Compensatory hyperinsulinemia and increased insulin production, in mice with transgenically enhanced galectin 3 expression, is enough to sustain relatively normal fasting glycemia compared to the control group on HFD but is insufficient after glucose load." (PMID 32117058, 2020). "In mice with transgenically overexpressed galectin 3, fasting glycemia was similar to the WT control group on HFD but with significantly higher compensatory hyperinsulinemia as a consequence of increased activity and insulin production by β cells." (PMID 32117058, 2020). "Insensitivity to insulin by other metabolic tissues can promote hyperinsulinemia, beta cell hyperplasia, and contribute to beta cell failure." (PMID 33187118, 2020). "Subsequently, hyperinsulinemia can lead to resistance to insulin through insulin receptor down-regulation." (PMID 33003490, 2020). "On high-fat feeding, male Pik3r1WT/Y657∗ mice remained hyperinsulinemia, but the difference between mutant and control mice was abolished by the greater increase in insulin concentrations in wild-type mice." (PMID 32439336, 2020). "The major finding indicated that 20E can improve whole body insulin sensitivity and reduce hyperinsulinemia." (PMID 32375750, 2020). "Generally, moderate levels of insulin suppress lipolysis efficiently in normal humans, but this effect will weaken in individuals with IR/hyperinsulinemia." (PMID 33014043, 2020). "Increased SeP levels promote insulin secretion from beta pancreatic cells contributing to hyperinsulinemia and IR; furthermore, SeP knockdown in the liver improves insulin sensitivity." (PMID 33266488, 2020). "As hyperinsulinemia is a known stimulus of SNS, lower insulin levels with pioglitazone associated with reduced sympathetic drive and the ability of TZDs to interfere with RAAS plays a significant role." (PMID 33170841, 2020). "At this time point, both STZ-sham and STZ-islets groups expressed hyperinsulinemia (8.95 ± 2.76 ng/ml and 8.72 ± 3.18 ng/ml, respectively) while intact rats showed normal level of serum insulin (0.91 ± 0.31 ng/ml)." (PMID 31929603, 2020). "The Mecr mRNA was elevated in the liver of DIO mice in the present study, which was likely a consequence of hyperinsulinemia in the DIO mice according to the insulin activity in the induction of Mecr mRNA in the cell culture model." (PMID 32440681, 2020). "In obese patients, the pre-diabetic state is accompanied by hyperinsulinemia as a consequence of a primary resistance of peripheral tissues to the action of insulin." (PMID 32492936, 2020). "DHA-rich fish oil also lowered IR and fasting insulin in individuals with abdominal obesity and hyperinsulinemia compared to the placebo group." (PMID 32486256, 2020). "Hyperinsulinemia has been shown to induce insulin resistance of DRG neurons through hyperphosphorylation of the InsR by an Akt-mediated pathway, and the increase in the expression of GSK-3-β." (PMID 32260335, 2020). "We demonstrate that β cell miR-26a markedly prevents HFD-induced hyperinsulinemia resulting from a decrease in β cell hyperplasia and insulin secretion." (PMID 32092075, 2020). "Hepatocyte-specific ablation of Sphk2 impaired insulin metabolic action and glucose homeostasis, as evidenced by marked glucose intolerance, decreased insulin sensitivity, and hyperinsulinemia." (PMID 32917816, 2020). "Gestational T treatment results in maternal hyperinsulinemia and disrupts insulin signaling in fetal metabolic tissues in sheep." (PMID 33158439, 2020). "In the present study, we focused on the skeletal muscle changes in this model and confirmed fasting hyperinsulinemia at 16 weeks of age prior to investigating expression of insulin signaling proteins in this fasting, hyperinsulinemic state." (PMID 33113794, 2020).
Hyperinsulinemia (continued). "In response to prolonged hyperinsulinemia, there is diminished autophosphorylation of the insulin receptor, compared to that observed after short-term exposure to insulin, and subsequent steps of the PI3K–AKT signaling pathway are affected." (PMID 32819363, 2020). "We recently found that long-term insulin therapy to induce hyperinsulinemia in rodents was sufficient to reduce the whole-body energy expenditure." (PMID 32872407, 2020). "Increased insulin secretion and reduced (that is, impaired) insulin clearance can contribute to hyperinsulinemia." (PMID 32860984, 2020). "Meanwhile, miR-26a prevents hyperinsulinemia through targeting several critical regulators of insulin secretion and β cell proliferation." (PMID 32092075, 2020). "In patients with hyperinsulinemia, insulin levels within the CNS are lower due to both reduced transport of insulin across the BBB and lower CNS insulin production." (PMID 32998245, 2020). "The tumor promoting effects of hyperinsulinemia were ameliorated by either lowering circulating insulin levels with a β3-adrenergic agonist, or with inhibitors of the IR/IGF-1R, PI3K, and/or mTOR." (PMID 33604295, 2020). "Considering the potential role of hyperinsulinemia in progression of MHO to MUO, meal plans associated with lower post-prandial insulin increments should potentially be of advantage." (PMID 32630256, 2020). "Both AE and Pp produced no significant change in the glucose level, but they effectively suppressed the effect of triton on the insulin level and prevented against mild hyperinsulinemia." (PMID 32308705, 2020). "Insulin-sensitizing drugs have been used as first-line treatment to improve hyperinsulinemia in women with PCOS." (PMID 32252239, 2020). "In the prediabetic insulin-resistant state, islets respond to the increased insulin demand by increasing insulin secretion and β-cell mass, which generates compensatory hyperinsulinemia and maintains relative normal glycaemia." (PMID 33067534, 2020). "Since the plasma insulin level of patients with T2DM is often higher than normal (hyperinsulinemia), the beta-cell mass in T2DM is thought to be increased or unchanged." (PMID 33339276, 2020). "Actually, rats under the status of IR will have a compensatory secretion of insulin, also named as hyperinsulinemia, to achieve the balance of glucose." (PMID 32928312, 2020). "Using the same animal model of prolonged hyperinsulinemia-induced laminitis, we previously reported similar disparity between insulin-sensitive tissues and lamellar tissue." (PMID 32596266, 2020). "PI3K inhibitors contribute to hepatic glycogenolysis and reduced glucose disposal into adipose tissue, leading to greater secretion of insulin from the pancreas and hyperinsulinemia." (PMID 33604295, 2020). "It is possible that SGBS need a longer exposure to high insulin stimulation to see more pronounced effects of hyperinsulinemia on glucose uptake." (PMID 32718202, 2020). "The increase in breast cancer due to T2D is ascribed to basal insulin resistance/hyperinsulinemia, with insulin acting as mitogenic growth factor." (PMID 32695336, 2020). "This is probably because the peripheral hyperinsulinemia after insulin treatment activates lecithin-cholesterol acyl transferase and hepatic lipase activities." (PMID 32149155, 2020). "Recent clinical evidence showed that MYO (1100 mg) and DCI (27.6 mg) acutely lowered insulin response after glucose intake in obese insulin-resistant male children with hyperinsulinemia." (PMID 32392776, 2020). "Insulin-mediated glucose disposal widely varies in its sensitivity across populations, and depending on the level of compensatory hyperinsulinemia, resistance to insulin can or cannot be overcome." (PMID 32867022, 2020). "HFD feeding induced hyperinsulinemia in mice and the treatment with Grb14-shRNA markedly decreased plasma insulin levels in mice under various nutritional states compared with the empty vector." (PMID 32099031, 2020).
Hyperinsulinemia (continued). "This leads to the formation of a specific vicious circle, i.e., hyperinsulinemia propels IR and weight gain, which, in turn, require higher insulin dosage for compensation." (PMID 33233346, 2020). "These treatments aimed to increase insulin sensitivity and to improve hyperinsulinemia, hyperandrogenism, ovulatory function and menstrual irregularity." (PMID 32917200, 2020). "Insulin levels during glucose tolerance testing showed the cohort of mice treated with L-5F had hyperinsulinemia similar to that of HFD-fed mice despite L-5F showing improved insulin sensitivity in the insulin tolerance test." (PMID 31914125, 2020). "In the fat group of sheep, high insulin concentrations (hyperinsulinemia) increased adipose tissue lipolysis and led to impaired NEFA uptake and an increase in plasma NEFA and triglyceride concentrations." (PMID 32545900, 2020). "Fasting hyperinsulinemia was observed in T2D pigs, as their plasma insulin levels were between 20 and 30 pmol/l and were significantly higher (p = 0.03) when compared to that observed in the healthy pigs." (PMID 33294459, 2020). "Early studies of male NZO revealed hyperglycemia, impaired glucose tolerance, hyperinsulinemia, and reduced insulin response following glucose stimulation (Larkins, 1973; Larkins, Simeonova, & Veroni, 1980)." (PMID 32374082, 2020). "The mechanism of action for metformin involves the improvement of hyperinsulinemia, androgen excess and anovulation by enhancing insulin sensitivity." (PMID 32456015, 2020). "Chronic exposure of the cells to insulin (HI; 100 nM, 24 h), to mimic hyperinsulinemia, increased GLUT4 plasma membrane levels (HI: 148% ± 8.6% of control, p < 0.0001)." (PMID 32230718, 2020). "The median fasting insulin levels (10.1 (6.1)) of the study participants indicate hyperinsulinemia, as the normal adult fasting insulin levels are <10 mIU/L." (PMID 32486256, 2020). "In case of hyperinsulinemia due to reduced insulin clearance, it is believed that there is a relative shift in signaling from the PI3K towards the MAPK pathway that ultimately results in endothelial dysfunction and vascular damage." (PMID 33384433, 2020). "As such periods of higher intracellular Ca2+ coincide with higher insulin secretion, we conclude that TMBIM6−/− islets secrete more insulin which is in line with the hyperinsulinemia observed during our hyperglycemic clamp experiments." (PMID 32394396, 2020). "Traditionally viewed as a compensatory response, insulin secretion is enhanced leading to hyperinsulinemia." (PMID 33038072, 2020). "IR has been shown to lead to hyperinsulinemia as a means to counteract the reduction in insulin action." (PMID 31991925, 2020). "The inhibitory effect of hyperinsulinism on glucagon is two-fold: mutation of the KATP channel affects alpha cell membrane potential/ glucagon secretion and high circulating insulin levels directly inhibiting secretion by the alpha-cell." (PMID 32735622, 2020). "The repression of Kir6.2/SUR1 channels stimulates the release of insulin, and it has been reported that mutations and deficiencies of ABCC8 and KCNJ11 induce hyperinsulinism." (PMID 32906679, 2020). "In most cases, persistent congenital hyperinsulinism is due to genetic defects in the pathway that regulate insulin secretion as outlined in a recent review." (PMID 31840185, 2020). "Another argument in favor of insulin as a cardiac growth factor is provided by the difference in mechanism, whereby hyperinsulinemia results in CH in unrelated diseases." (PMID 31840185, 2020). "Elevated insulin concentrations indicate hyperinsulinism, which suppresses the production of alternative metabolic fuels, and hence maintaining blood glucose ≥ 3.5 mmol/l is recommended." (PMID 33489995, 2020). "In persistent congenital hyperinsulinism, there is a focal or diffuse overproduction of insulin by the pancreas secondary to various genetic disorders." (PMID 31840185, 2020).